RAC1 (Rac family small GTPase 1)
Diseases named in the same sentence as RAC1 in open-access papers (continued):
Sharing a sentence is not in itself a finding about the gene and the disease.
tongue squamous cell carcinoma (1 paper, 2021). A squamous cell carcinoma that arises from the tongue. "In addition, the inhibitory effect of ERK3 on cell migration in tongue squamous cell carcinoma cell line by downregulating Rac1 level was also reported." (PMID 33579235, 2021).
uremia (1 paper, 2013). A clinical syndrome associated with the retention of renal waste products or uremic toxins in the blood. "The effect of uremia on platelet function may be reflected by changes in the probe sets coding for PKCeta, Rac1, ATP2A3, and GP-IB (platelet glycoprotein I beta) and other members of the “platelet aggregation” network." (PMID 23809614, 2013).
ureteric obstruction (1 paper, 2024). "After the relief of ureteric obstruction, Rac1 promoted actin cytoskeletal reconstitution, which was required to maintain normal mitotic morphology allowing for successful cell division." (PMID 38324689, 2024).
Usher syndrome (1 paper, 2018). A syndromic diseae characterized by the association of sensorineural deafness (usually congenital) with retinitis pigmentosa and progressive vision loss. "Although not implicated in Usher syndrome, Rac1, which encodes a small GTPase, also appears to similarly affect bundle maturation." (PMID 30157177, 2018).
ventricular tachycardia (1 paper, 2016). A disorder characterized by an electrocardiographic finding of three or more consecutive complexes of ventricular origin with a rate greater than a certain threshold (100 or 120 beats per minute are commonly used). "Our data show that the number of singlet and doublet ventricular premature beats and the incidence of ventricular tachycardia were significantly decreased by both pharmacological and genetic inhibition of Rac1." (PMID 27222313, 2016).
Wilms tumor (1 paper, 2020). An embryonal neoplasm characterized by the presence of epithelial, mesenchymal, and blastema components. "Staining of the Wilms tumor cells with a RAC1 antibody revealed that lamellipodia can be observed at several sites on the cell and not only in the direction of movement." (PMID 33379206, 2020).
ZIKV infection (1 paper, 2023). "Only a few mRNA’s were downregulated, but notably, these included Rac1/RhoA, which are GTPases with known roles in maintaining a neural progenitor cell pool and neuronal development, that we have previously proposed may be relevant to ZIKV infection in the developing brain." (PMID 37022660, 2023).
cancer (738 papers, 2008 to 2026). A tumor composed of atypical neoplastic, often pleomorphic cells that invade other tissues. "Evaluating the expression of protein markers, particularly Rho GTPases linked to carcinogenesis and various cancers, we have demonstrated that overexpression of RhoA and Rac1, members of the Rho GTPase family, is associated with cancer progression." (PMID 39887960, 2025). "Rho family GTPases, including Rac1, are primarily associated with cancer metastasis due to their regulation of cytoskeletal dynamics." (PMID 41360259, 2025). "Rac1 is a small GTPase protein that plays a role in cell adhesion, migration, and proliferation; therefore, Rac1 mutations and aberrant activity are linked to cancer development." (PMID 40943055, 2025). "RAC1, a member of the Rho family GTPases, has been implicated in various cancers, yet its pan-cancer landscape and role in the tumor immune microenvironment remain underexplored." (PMID 39898257, 2025). "An integrated analysis of the three indicators revealed that higher expression of RAC1 is associated with poorer clinical prognosis, identifying RAC1 as a hazard factor for many cancers." (PMID 39898257, 2025). "This study presents a comprehensive analysis of RAC1 across 33 cancer types, revealing its high expression in a broad range of cancers and its association with poor prognosis." (PMID 39898257, 2025). "Our results uncover a novel isoform-dependent GTPase:effector binding mode for Rac1-driven actin dynamics, with implications for therapeutic targeting in Rac1-associated cancer progression." (PMID 41360259, 2025). "Some clinical investigations have reported that Rac1 is overexpressed in cancer cells and is implicated in tumor growth, metastasis, and drug resistance." (PMID 40943055, 2025). "The deficiency of HACE1 leads to the hyperactivation of Rac1, resulting in increased cellular malignancy and invasiveness, thereby promoting cancer progression." (PMID 40948788, 2025). "The dysregulation of RAC1 activity is associated with neoplastic transformation, metastasis, and poor prognosis in several cancers." (PMID 40633540, 2025). "Beyond RCC, RAC1 functions as a pan‐cancer biomarker, whose overexpression is consistently associated with poor prognosis, heightened metastasis, and immunosuppressive traits, highlighting its potential as a therapeutic target." (PMID 41498044, 2025). "Overall, these findings suggest that high RAC1 expression is generally associated with lower stromal and immune scores in the tumor microenvironment of most cancers." (PMID 39898257, 2025). "In conclusion, the CGN c.3560C > T variant leads to overexpression of IQGAP1 and activation of Rac1, correlating with metastasis and drug resistance in cancer cells." (PMID 38424547, 2024). "Rac-1 and its mutated derivatives play a significant role in the progression of various cancers through their molecular signaling." (PMID 39161777, 2024). "As a result of this analysis, high expression of RAC1 was associated with the largest number of cancer types, nine of which had poor survival." (PMID 38968580, 2024). "A recent study has shown that elevated C1GALT1 expression is associated with poor prognosis and contributes to cancer cell proliferation, migration, and invasion through upregulating RAC1 in LUAD." (PMID 38662050, 2024). "In human cancers, gain of function mutations in RAC1 result in increased RAC1 signalling which contributes to cancer cell growth and invasion of local and distant tissues." (PMID 40396280, 2024). "Rac1 hyperactivation is a hallmark of a variety of cancers, contributing to enhanced cancer cell migration, invasion, and metastasis." (PMID 38191532, 2024). "The P29S mutation in the Rac1 gene is a specific alteration that has been identified in various cancers and is associated with oncogenic activity." (PMID 39161777, 2024).
cancer (continued). "Deregulated Rac1 expression and/or activity is a common event in cancer, and has been associated with anchorage-independent growth, transformation, migration, and invasion." (PMID 38191532, 2024). "Both in vitro and in vivo studies indicate that wild-type RAC1 has an essential role in RAS-mediated transformation, and RAC1 overexpression is linked to worse prognosis in cancer patients." (PMID 40396280, 2024). "Studies have shown that ITGB6 can activate Rac1 signaling in epithelial cells, leading to changes in cell behavior that are associated with cancer progression." (PMID 38344200, 2024). "In cancer, RAC1 can be overexpressed or mutated to become constitutively active, but RAC1 is more likely to be overexpressed in CRC." (PMID 39001533, 2024). "This overexpressed IQGAP1 was consistently associated with the activation of Rac1, as evidenced by the analysis of the cancer cell line and clinical sample harboring CGN c.3560C > T." (PMID 38424547, 2024). "Rac1, a widely expressed Rho GTPase, is a major player in the assembly of actin-rich membrane protrusions (i.e., ruffles) implicated in cancer cell migration." (PMID 38612674, 2024). "Hyperactivation and/or overexpression of Rac-GEFs have been linked to aberrant activation of Rac1 in cancer." (PMID 38191532, 2024). "RAC1 subcellular localization unbalance and abnormal nuclear accumulation has been linked to cancer progression and invasion." (PMID 40396280, 2024). "Targeting activated Rac1 is a strategy to impede the advancement of cancers carrying this specific variant." (PMID 38424547, 2024). "On the contrary, increased cell motility due to hyperactivation of Rac1—by drugs, point mutations, or the expression of the Rac1b splice variant—can promote the spreading of different cancers through metastasis." (PMID 38534316, 2024). "The loss of HACE1 leads to an increase of RAC1 activity that contributes to tumour growth, cell migration and cancer progression." (PMID 40396280, 2024). "Rac1 hyperactivation in cancer cells is frequently caused by the oncogenic activation of upstream GEFs, or by the dysregulation of GEF expression or activity." (PMID 38191532, 2024). "Co-expression network showed genes closely associated with RAC1 were calculated among which cancer genes such as MUC1, MUC20, CEACAM5, andCCL20 were positively correlated to expression of RAC1 whereas TIMP3 and MGP was negatively correlated." (PMID 37202394, 2023). "Rac-1 and Cdc42 are known to be over-expressed in several cancers and is associated with poor prognosis and drug resistance." (PMID 37024613, 2023). "Down-regulated Rac1 expression or loss of its function significantly suppressed cancer cell proliferation and metastasis." (PMID 37612265, 2023). "The small GTPase Rac1 (Ras-related C3 botulinum toxin substrate 1) has been implicated in cancer progression and in the poor prognosis of various types of tumors." (PMID 38098337, 2023). "Bioinformatic results show that RAC1 is highly expressed in cancer and that high expression is associated with a worse prognosis." (PMID 38041179, 2023). "For example, recent studies have shown that genetic mutations lead to an increase in Rac1 activity or expression, which promotes cancer cell development, progression, and leads to a poor patient prognosis." (PMID 38147021, 2023). "RAC1 signaling is frequently deregulated in cancer through mutations or overexpression of RAC1 guanine nucleotide exchange factors (GEFs) or RAC1 itself." (PMID 37748077, 2023). "The finding is in line with that Rac1 overexpresses in various tumors is closely associated with tumor migration, invasion and poor prognosis of carcinomas." (PMID 37612265, 2023). "Some additional cancer-associated mutants in RAC1 and RAC2 have been reported in common cell lines and are given in public databases." (PMID 35454871, 2022).
cancer (continued). "Rac3, a member of the p21 Rho family of small GTPases, is an understudied paralog of the canonical Rac1 GTPase and has been implicated in cancer cell proliferation, invasion, and autophagy." (PMID 36555156, 2022). "A substantial number of cancer-associated point mutations in predominantly RAC1, RHOA, and CDC42 have been found and characterized." (PMID 35454871, 2022). "Rac1 is a cytoskeleton involved in cell adhension, morphology, and movement; overexpression of Rac1 is associated with unfavorable survival in different type of cancer." (PMID 35280744, 2022). "PAK5 (formerly PAK7) is an actin‐ and microtubule‐associated, p21cdc42/rac1 ‐activated kinase family member, which has been shown to promote proliferation, invasion, and migration of various cancer cell models." (PMID 35225431, 2022). "Overexpression of P29S mutation after UV exposure is reportedly involved in cancer proliferation and migration through Cdc42 and Rac1." (PMID 34201921, 2021). "The expression levels of three gene targets correlated with the risk scores, demonstrating that elevated hTERT, Rac1, and Cdc42 levels are associated with cancer recurrence and poor prognosis." (PMID 33510789, 2021). "Of these, only RhoA and Rac1 appear significantly mutated in a narrow spectrum of human cancers, although alterations to their levels of expression are frequent." (PMID 34071831, 2021). "Those therapies would attempt avoiding the appearance of drug resistance related to RAC1 mutations, procuring a new molecular weaponry against cancer." (PMID 34827551, 2021). "As such, activated RAC1 relays transforming information downstream of over-expressed FAK or mutated KRAS in cancer cells, mainly by binding to and activating its effectors PAK1-3." (PMID 34638434, 2021). "One option would be to inhibit specific cancer-associated RAC1-GEFS, an approach exemplified by inhibitors such as NSC23766, a small-molecule inhibitor which blocks the interaction of a subset of GEFs, including TIAM1, with RAC1." (PMID 33397922, 2021). "Metastasis, migration and invasion associated cancer genes such as RanGAP1 (Ran-GTPase activating enzyme 1), Rho-like GTPase- Rac1, MMPs like MMP-9, MMP-14 and slug are found to be profoundly SUMOylated." (PMID 34715855, 2021). "Loss of CYRI-A and -B promoted cancer cell invasion, presumably because of excess active integrins on the cell surface and perhaps higher overall levels of RAC1 activation and engagement of the Scar/WAVE complex at the cell’s leading edges." (PMID 34165494, 2021). "Aberrant expression of RAC1 is recognized as a hallmark of cancer and contributes to the tumorigenic and metastatic phenotypes of cancer cells." (PMID 34307388, 2021). "Experiments using genetically modified mouse models revealed that tissue-restricted genetic loss of Rac1 impaired mutant K-Ras-driven lung and pancreatic cancer development." (PMID 34071831, 2021). "Based on the signaling outcomes from Rac1 or Cdc42 activation, overexpression of each protein has been implicated in cancer growth, progression and metastasis, chemoresistance, and for some tumors, poor patient outcomes." (PMID 33413202, 2021). "Elevated Rac1 activation has been largely associated with the progression of various cancers and metastatic dissemination of cancer cells." (PMID 32092966, 2020). "Our study highlights a possible therapeutic strategy for IDH1-mutated cancers by targeting the endocytosis pathway, such as the mTORC2/Rictor/Rac1 axis." (PMID 32224866, 2020). "Rac1, in particular, contributes to cancer development, stimulating cell proliferation and loss of cell polarity and by altering cell-to-cell and cell-to-matrix junctions, it promotes migration and invasion to distant sites." (PMID 32351958, 2020). "Recent studies have identified activating mutations in Rho GTPases, such as RhoA, Rac1, and Cdc42, in various human cancers." (PMID 32392742, 2020).
cancer (continued). "As a driver of motility and cell cycle progression, the Rac1–Scar/WAVE pathway is linked to cancer progression and metastasis in many tumour types." (PMID 32057095, 2020). "The recent efforts in next-generation sequencing have revealed that Rho GTPases are mutated in a variety of cancers, and recurrent mutations in RAC1 and RHOA have been identified." (PMID 32526908, 2020). "The overexpression of RhoA and Rac1, members of the Rho GTPases, have been linked with carcinogenesis and the progression of different types of cancer." (PMID 32731493, 2020). "RHOA is recognized as driver gene in DLBCL and RAC1 is recurrently mutated or upregulated in cancers." (PMID 32349449, 2020). "In summary, this study demonstrated that IDH1-mutated cancer cells exhibit increased endocytosis through activation of the mTORC2/Rictor/Rac1 axis." (PMID 32224866, 2020). "Another contribution of RAC1 to the oncogenic transformation of cancer cells occurs through the RAC1b splice variant." (PMID 32545340, 2020). "RAC1 overexpression has been implicated in cancer cell proliferation (a hallmark of cancer), progression, and resistance." (PMID 32545340, 2020). "RAC1 can also be activated by MET-associated complex in various cancer cells and promotes migration and invasion." (PMID 33204717, 2020). "Recently cancer-associated gain-of-function (GOF) mutations in RAC1 have been identified, which are responsible for aggressive tumor phenotypes and confer resistance to targeted therapies." (PMID 32545340, 2020). "The GTPase RAC1 plays a crucial role in regulating cell migration, and it has been implicated in cancer cell progression." (PMID 31578236, 2019). "RhoA or RAC1 are mutated in a few cancers, but in most cancers, expression levels and/or activity of Rho GTPases is altered via a number of regulatory mechanisms." (PMID 31027363, 2019). "In the last years, several studies have linked PKC to the activation of Rac1 and cancer cell motility." (PMID 31515469, 2019). "The COSMIC database show that more than one RAC1 mutation can occur in different cancers types, which includes the large intestine, cervix, liver, endometrium, stomach, esophagus, lung, upper aero-digestive tract, hematopoietic/lymphoid, and breast." (PMID 31027363, 2019). "The members of Rho GTPases, Rac1, Cdc42, and RhoA, have been considered as classical cytoskeleton regulators associated with cancer cell migratory phenotype." (PMID 31019460, 2019). "The role of Rac1 in the acquisition of invasive and metastatic phenotypes and thus cancer progression has been well established, and increased expression of Rac1 has been associated with poor prognostic outcome for a number of cancers." (PMID 31515469, 2019). "More recently, cancer-associated gain-of-function mutations in RAC1 have been identified which contribute to tumor phenotypes and confer resistance to targeted therapies." (PMID 31027363, 2019). "Because aberrant RAC1 GTPase signaling activities are widely associated with human cancer, key components of RAC1 GTPase signaling pathways have attracted increasing interest as potential therapeutic targets." (PMID 31027363, 2019). "Despite the low frequency of RAC1 gene mutations, RAC1 is similar to well-known oncogenes and tumor suppressors in being categorized as a Tier 1 cancer-causing gene in the COSMIC cancer gene census." (PMID 30261690, 2018). "The identification of cancer-associated somatic mutations in Rac1 and RhoA, and more recently also in Cdc42, has demonstrated that the Rho GTPases appear to have more active roles in cancer progression than originally thought." (PMID 30544828, 2018). "The first mutant Rho member that was linked to cancer was a splice variant of Rac1 that is known as Rac1B." (PMID 30544828, 2018).